EGR1 (early growth response 1)
Diseases named in the same sentence as EGR1 in open-access papers (continued):
Sharing a sentence is not in itself a finding about the gene and the disease.
tumor (continued). "We found that the positive rate of tumour cell TUNEL staining in the BRC-treated group was significantly higher than that in the control group and that the EGR1 and p-ERK1/2 expression levels were also significantly higher in the BRC treatment group than in the control group." (PMID 31000722, 2019). "Except for few being chromatin regulators (CGBP, MBD2, and DNMT1), all of these TFs were found to have tumor suppressor functionality (BRCA1, E2F1&2&5&7, EGR1-4, FLI1, NRF1, TFDP2, and STAT1), or indirectly mediate the suppression of tumorigenesis and tumor suppressor activity (SP4 and ZBTB33)." (PMID 29740534, 2018). "OASL, EGR1, and BMP2 were significantly downregulated in tumor in GSE13861." (PMID 30134903, 2018). "To confirm that these changes could be seen in human tumors, we performed immunohistochemistry on tumor tissue from two independent tumors from both ERMS and ARMS patients and found that ERMS tumors expressed higher EGR1 levels than ARMS tumors." (PMID 29719592, 2018). "Egr-1 is an important regulator of cell proliferation, apoptosis, metastasis, and EMT in the progression of kinds of cancers including PCa and functions as a tumor suppressor in various of cancers." (PMID 30333255, 2018). "In addition, Egr1 regulates the expression of a large number of genes required for suppressing HCC growth, including PTEN, a very well known tumor suppressor that inhibits PI3K signaling pathway in HCC." (PMID 29607419, 2017). "Immunohistochemical staining of these proteins in biopsies from human OvCa peritoneal implants showed mesothelial‐derived (calretinin‐positive) spindle‐like cells in the stroma tissue surrounding tumour nodules, overlapping with areas with marked staining for MMP1, IL‐33, EGR1, TSP1, and GREM1." (PMID 28247413, 2017). "Moreover, as was the case in vitro, RAC1, p22phox, EGR1, and PTEN expression were higher in tumor tissues from EGF-treated mice compared to tumor tissues from PBS-treated control mice." (PMID 27935858, 2017). "Some of the up-regulated genes act as tumor suppressors (TXNIP, EGR1, and PPP1R15A)." (PMID 28035074, 2017). "The second most down-regulated gene was neuritin 1 (NRN1), which has been proposed as hypoxic marker and potential marker for tumor angiogenesis, followed by the proline-rich nuclear receptor coactivator 2 (PNRC2), syntaxin 19, and early growth response 1 (EGR1)." (PMID 28402269, 2017). "Importantly, significant reductions in EGR1 and HOXB9 levels were observed in tumours following two doses of miR-192-DOPC treatments, compared with tumours treated with control miRNA-DOPC." (PMID 27041221, 2016). "Furthermore, overexpression of EGR1 in LS174T cells promoted cell growth in vitro and tumor growth in our animal model." (PMID 27442508, 2016). "Only minimal decreases in MVD and increases in the extent of pericyte coverage of residual blood vessels were observed in tumours expressing both EGR1 and HOXB9 after the miR-192 treatments, emphasizing the key roles EGR1 and HOXB9 play in mediating the anti-angiogenic effects of miR-192." (PMID 27041221, 2016). "We next assessed whether the anti-angiogenic effect of miR-192 can be abrogated by EGR1 and/or HOXB9 expression in SKOV3ip1 tumours." (PMID 27041221, 2016). "The central role of EGR1 and HOXB9 in tumour angiogenesis has recently been recognized." (PMID 27041221, 2016). "In addition, MSK1 and MSK2 facilitate the stress-induced phosphorylation of CREB at Ser-133, which induces the transcription of several immediate early genes including c-fos, junB, and egr1, which are, notably, part of the low-TTP tumor gene signature." (PMID 25541715, 2014). "ZNF268 may be similar to Egr1, which has been identified as a target of GATA-1 by ChIP-seq analysis and is regarded as a tumor repressor." (PMID 22235304, 2012). "Both EGR1 and PTEN have been reported to be downregulated by the specific microRNA, miR-183, and the elevated level of miR-183 has been observed in SS and other tumor types." (PMID 22550415, 2012).
tumor (continued). "In addition, miR-183 functioned as an onco-miRNA, shown to target the tumor suppressor transcription factor early growth response 1 (EGR1), and phosphatase and tensin homolog (PTEN) to promote tumor cell migration." (PMID 21920043, 2011). "Another exception to the pattern of elevated expression in tumor tissues of genes identified in epithelial cells, was the significantly higher EGR1 expression in non-neoplastic compared to tumor tissues (p < 0.05, paired t-test)." (PMID 20426842, 2010). "Surprisingly, EGR1 expression was consistently lower in tumor tissues relative to non-neoplastic tissues for both stage T2 and T3 tumors." (PMID 20426842, 2010). "This lack of elevated EGR1 expression in tumor tissue was consistent with the results of the real-time PCR quantitation of expression in microdissected tissue." (PMID 20426842, 2010). "Again, both tumor and stroma lacked Egr-1, making it difficult to assess the contribution of these two compartments." (PMID 19200397, 2009). "Previous studies have shown that manipulating Egr-1 expression can have either positive or negative effects on tumor growth." (PMID 19200397, 2009). "The suppression of the genes EGR1 and STAT1 correlates with active tumor formation." (PMID 18811983, 2008). "Strikingly, treatment with metformin might reduce tumor growth, mainly by inducing the expression of a set of genes FOSB, EGR1, ZFP36, GPR183, ATF3, and NR4A1 which are involved in DNA-binding transcriptional activation, response to hormones and the Dcp1-Dcp2 mRNA-decapping complex." (PMID 39026155, 2024). "EGR1, a transcription factor involved in growth and differentiation, and P2RY6, a receptor gene involved in immune and inflammatory responses, indicate significant transcriptional changes in platelets potentially aiding tumor manipulation of the host environment." (PMID 39001461, 2024). "To confirm the role of WTAP, EGR1, and PTEN in tumor growth in vivo, we constructed xenograft tumor models in nude mice by subcutaneous injection of overexpression of WTAP, EGR1, and PTEN in ECCs and ECSCs, respectively, or combined overexpression of WTAP + EGR1 or EGR1 + PTEN." (PMID 39044249, 2024). "This is due to the induction of phosphorylation in tumor cells by cytotoxic T-cell immunotherapy, which specifically targets the transcription factors signal transducer and activator of transcription 3 (STAT3) and early growth response-1 (EGR-1) and subsequently promotes the formation of CIC." (PMID 37637068, 2023). "The increased transcripts for EGR1, interferon-induced proteins (IFI6, IFIT1, IFIT3, IFIT5), and MHC class II (HLA-DRA) indicated strong stimulation of IFN signaling, which could result in activation of macrophages in the tumor microenvironment." (PMID 37834191, 2023). "We detected 24 genes across the tumor tROIs that showed a high CV (i.e., were among the genes with the top 20% highest CV in seven out of seven cases), such as multiple collagens (COL1A1, COL1A2, COL3A1, COL5A1, COL5A2), S100A8, S100A9, FN1, or Early growth response protein 1 (EGR1)." (PMID 37511126, 2023). "We showed that the expression of EGR1, EGR2, EGR3, and EGR4 was significantly lowered in HCC specimens in comparison to nontumor specimens, which suggested that members of the EGR family may serve as a tumor suppressor in the progression of HCC." (PMID 36046377, 2022). "WT1 was originally considered a tumor suppressor gene, repressing the transcription of several growth factors and growth factor receptors including insulin-like growth factor II, insulin-like growth factor receptor, PDGF, TGF β1, PAX2, retinoic acid receptor α and EGR1." (PMID 36818371, 2022).
tumor (continued). "Since NTRK1 is a target of EGR1, the central hub involved in NAB2-STAT6-dependent deregulation of gene expression, our results may suggest that an increased EGR1 transcriptional program could lead to a more aggressive tumor phenotype." (PMID 34680383, 2021). "In addition, EGR1 supports FGF-dependent angiogenesis during neovascularization and tumor growth." (PMID 29127420, 2017). "We propose a model of CISD2–ROS–EGR1/GPX3 axis signaling, in which increased levels of CISD2 contribute to the neutralization of excessive ROS production, which would otherwise increase antitumor activity mediated at least by the tumor suppressors EGR1 and GPX3." (PMID 28928421, 2017). "The results suggest EGR1 showing lower expression in cancer tissues compared with normal tissues maybe still play an important role in tumor proliferation." (PMID 29246166, 2017). "Our data support a model in which KLF4 is activated in GSC downstream of the MAPK pathway in part through EGR1, and we further demonstrate that EGR1 acts as a transcriptional regulator of KLF4 in GSCs in-vitro, and its expression level positively correlates with KLF4 in clinical GBM tumor samples." (PMID 28256619, 2017). "Depending on the cell type, the duration and intensity of the stimuli, EGR-1 can act as a tumor repressor by inducing necrosis/apoptosis, block of angiogenesis and proliferation arrest, or can promote EMT-mediated cell migration, invasion, tumor growth, and acquisition of chemo-resistance." (PMID 28758926, 2017). "Our previous study found that EGR1 gene expression is downregulated comparing tumour versus normal." (PMID 27671774, 2016). "Nevertheless we can confirm 6 of their identified genes (SPP1, TOP2A, AREG, EGR1, CD34, and IGF1) as well as one of the identified miRNAs (hsa-miR-101), that they found to be differentially expressed in lymph node metastases compared to primary tumours and to normal tissue." (PMID 26537449, 2015). "Importantly, genes co-expressed with SLC16A7/MCT2 in human tumours also clustered in oncogenic-related pathways (e.g. PI3K, EGFR, KRAS) and effectors of these signalling pathways were found to bind at the SLC16A7/MCT2 gene locus (e.g. MYC, EGR1, PRDM1)." (PMID 26035357, 2015). "Importantly, earlier research has not defined a role for EGR1 in MDSC although it has been shown to induce transcription of a matrix metalloprotease 9 gene in tumor microenvironment." (PMID 25294811, 2014). "However, although several studies have shown EGR-1 promotes cancer progression, there is increasing evidence that EGR-1 may also exerts tumor suppression." (PMID 22461839, 2012). "With the exception of the DU145 cells, WT1 and EGR1 expression levels were consistent with the frozen paired tissue samples examined; that is, WT1 expression was elevated (p < 0.05) and EGR1 expression reduced (p < 0.001) in tumor cell lines relative to RWPE-1 prostate epithelial cells." (PMID 20426842, 2010). "We speculated that the absence of Egr-1 in the stromal tissue of mice might have an effect on tumor growth, possibly due to dysregulation of angiogenic signalling." (PMID 19200397, 2009). "However, 13-cis-RA did not significantly modulate RET, RGS16, FLNB, and EGR1 expression in the tissue samples from tumour-bearing animals treated for 5 days." (PMID 16012519, 2005). "Furthermore, it has been reported that the early growth response protein Egr1 and the copper-dependent monooxygenase Moxd1, which were found to be significantly increased in NTBC-treated HT1 livers, are correlated to the invasiveness of HCC cells and early tumor development, respectively." (PMID 36980965, 2023).
tumor (continued). "Therefore, Egr-1 might be a new and interesting target of anti tumor therapy especially when anti-hormonal drugs are no longer effective." (PMID 23202940, 2012). "Inhibition of STAT3 and EGR1, but not MAPK3 and EGR2, significantly abrogated the capacity of tumor cells to form cell-in-cell structures upon incubation with IFNγ-stimulated T cells and with T cell secreted granules." (PMID 36124553, 2022). "It was found the EGR1 expression was not relevant to the age and sex of patients but correlated with advanced tumor node metastasis (TNM) staging and increased tumor size." (PMID 34409922, 2021). "For instance, EGR1 and USF2 were highly co-expressed in the tumor sample (scLink’s correlation = 0.77, P = 0.01) but not in the normal sample." (PMID 34252628, 2021). "While EGR1 has been described as having both positive and negative functions in tumor development, our data suggest that in TNBC, EGR1 promotes tumor progression under the control of ERK2." (PMID 32444778, 2020). "The relative expressions of EGR1, FOS, and FOSB mRNA were 0.493±0.558-, 0.494±0.476-, and 0.500±0.551-fold downregulated in 20 tumor tissues versus adjacent nontumor tissues, respectively." (PMID 30228980, 2018). "In contrast, the tumours expressing EGR1 and HOXB9 proteins failed to respond to miR-192 therapy, again demonstrating the central role of these two proteins in miR-192-mediated anti-tumour effect." (PMID 27041221, 2016). "Survival analysis revealed that SNAT1 is an important predictor for tumor recurrence and prognostic factor for HC patients, while UCHL1 and EGR1 was not a significant indicator of prognosis." (PMID 25971332, 2015). "Although TNF secretion was mediated by Egr-1, TRAIL secretion only occurred in a tumour cells line that did not express functional Egr-1." (PMID 20087343, 2010). "This impediment correlates with overexpression of Mig in the tumor, a phenomenon that is not observed in B16F10 tumors, which do not exhibit slower growth in Egr-1-/- mice." (PMID 19200397, 2009). "We have shown that mice lacking Egr-1 have impaired growth of LLC1 tumors, and that this correlates with increased expression of Mig in the tumor." (PMID 19200397, 2009). "EGR1 was upregulated upon knockdown of LSR in vitro and upregulated when comparing tumor samples with normal urothelium samples, though not significantly." (PMID 18647386, 2008).
cancer (332 papers, 2007 to 2026). A tumor composed of atypical neoplastic, often pleomorphic cells that invade other tissues. "Although some studies have shown that early growth response factor 1 (EGR1) has a significant role in cancer development and progression, its role and underlying mechanisms in ccRCC remain poorly understood." (PMID 39866235, 2025). "FTO supports cancer-associated fibroblast-mediated angiogenesis through the activation of early growth response 1 (EGR1) and VEGFA." (PMID 40429638, 2025). "Among the 23 NFκB/TNF hallmark genes voted in all 16 cancer types, EGR1, JUNB, and ZNF36 exhibited an average vote of 1,000." (PMID 37475016, 2023). "EGR1 has also been implicated in apoptosis, most notably in cancer studies where EGR1 expression is significantly reduced in developing tumors." (PMID 35746681, 2022). "For example, EGR1 is linked to cancer suppression due to cell cycle arrest and apoptosis by regulation of cancer suppressor pathways." (PMID 35999505, 2022). "We also predict transcription factors that lead to hyper-methylated regions upon transcription factor loss such as EGR1 in several cancer types." (PMID 35331302, 2022). "EGR1 is reported to be a cancer suppressor gene and the downregulating of EGR1 in OS samples was usually associated with poor prognosis." (PMID 34252359, 2021). "And an increasing number of studies have shown that EGR1 is highly associated with cancer development and progression." (PMID 32974202, 2020). "The upregulation of EGR1 upon bacterial infection is therefore a possible important event in bacteria-associated cancer development." (PMID 28180113, 2017). "Aberrant EGR1 expression is linked to human diseases such as ischemic injury, cancer, inflammation, atherosclerosis, and cardiovascular pathogenesis." (PMID 27244890, 2016). "Activation of MAPK increases the expression of the Early Growth Response 1 (EGR1) transcription factor which in turn is linked to key cancer processes such as growth and cell survival." (PMID 25546138, 2014). "EGR1 has been implicated as a cancer suppressor gene and activates genes required for differentiation." (PMID 18631392, 2008). "EGR1 has also been implicated in cancer cell growth, EMT, and metastasis." (PMID 40204777, 2025). "Several researches suggest that EGR1 is implicated in developing resistance to cancer treatments." (PMID 39866235, 2025). "High expression of EGR1 was also associated with poor prognosis in cancer patients." (PMID 38244586, 2024). "Also, EGR1 level was found to be relevant to the genes encoding angiogenic/osteoclastogenic pathway effectors and to directly affect cancer metastasis." (PMID 34409922, 2021). "Our result confirmed that the deactivation of EGR1 was associated with cancer aggressiveness." (PMID 34497759, 2021). "Low levels of EGR1 have been implicated in chemotherapeutic resistance in two other cancers." (PMID 29719592, 2018). "Nevertheless, EGR1 is functionally implicated in numerous critical biological processes, including inflammation, cell proliferation, differentiation, vascular wound response, and cancer progression." (PMID 29546053, 2018). "Although IR-induced upregulation of Egr-1 and autophagy have been implicated in cancer radioresistance, the precise role of Egr-1 and autophagy in this aspect especially in HCC remain unclear." (PMID 28134935, 2017).